MASP2 (MBL associated serine protease 2)
Description:
Precursor of a serum protease that activates the lectin pathway of the complement system, a cascade of proteins that leads to phagocytosis and breakdown of pathogens and signaling that strengthens the adaptive immune system. The lectin complement system is activated following association of lectins, such as MBL2, FCN1, FCN2 or FCN3, to carbohydrates on the pathogen surface. MASP2 is cleaved and activated by MASP1 in response to lectin-binding to pathogen carbohydrates. Can activate prothrombin to thrombin. [Mannan-binding lectin serine protease 2 B chain]: Serine protease component of the lectin complement pathway, which catalyzes cleavage and activation of C2 and C4, the next components of the complement pathway.
Synonyms: MASP-2; Map19; sMAP; MAP-2; MASP1P1
Tractability: Small molecule: it has a binding pocket of medium quality. Antibody: a drug acting on it is in phase 2 or 3 trials; its Gene Ontology location is reachable by antibodies, with high confidence; UniProt places it where antibodies can reach, with medium confidence; UniProt predicts a signal peptide or a membrane-spanning region. PROTAC: a small molecule that binds it is known.
Target class: Enzyme; Hydrolase
Gene: Protein-coding gene on chromosome 1 (11,022,009 to 11,047,241, reverse strand). Ensembl gene ENSG00000009724.
Subcellular location: Secreted; Secreted (Mannan-binding lectin serine protease 2 B chain); Cell surface
Subcellular location (Human Protein Atlas): Golgi apparatus; Predicted to be secreted
Pathways (Reactome):
Immune System: Ficolins bind to repetitive carbohydrate structures on the target cell surface; Initial triggering of complement; Lectin pathway of complement activation
Disease: SARS-CoV-2 activates/modulates innate and adaptive immune responses
Gene Ontology:
Molecular function: calcium-dependent protein binding; complement component C4b binding; peptidase activity; protein binding; serine-type endopeptidase activity; calcium ion binding
Biological process: complement activation, lectin pathway; complement activation; proteolysis
Cellular component: cell surface; extracellular exosome; extracellular region; Golgi apparatus
Genetic constraint (gnomAD): Loss-of-function variants: 41 observed, 45.89 expected, observed/expected ratio (o/e) 0.89, 90% interval 0.69 to 1.16. The upper end of that interval is the gene's LOEUF score, 1.16, which puts it in group 5 of 6, group 1 being the genes least tolerant of losing a copy. Missense variants: 835 observed, 819.04 expected, observed/expected ratio (o/e) 1.02, 90% interval 0.96 to 1.08. Synonymous variants: 356 observed, 317.04 expected, observed/expected ratio (o/e) 1.12, 90% interval 1.03 to 1.23.
Homologues: Orthologues: chimpanzee MASP2 (99% identical), macaque MASP2 (95% identical), pig MASP2 (82% identical), mouse Masp2 (81% identical), rat Masp2 (80% identical), dog MASP2 (80% identical), tropical clawed frog masp2 (50% identical), zebrafish masp2 (48% identical). Paralogues in human: MASP1 (43% identical), PRRG2 (7% identical).
Diseases named in the same sentence as MASP2 in open-access papers:
MASP2 is named in the same sentence as 141 diseases in open-access papers, as found by Europe PMC text mining. Sharing a sentence is not in itself a finding about the gene and the disease. The quoted sentences say what the papers report.
COVID-19 (50 papers, 2020 to 2025). A disease caused by infection with severe acute respiratory syndrome coronavirus 2. "Skin and lung tissue examinations from 5 patients with severe COVID-19 revealed deposition of C5b-9, C4d, and mannose-binding protein-associated serine protease 2 (MASP-2) in the microvasculature, consistent with complement-mediated microvascular injury." (PMID 40993743, 2025). "The particularity of COVID-19 is related to the lectin pathway component, the mannose-associated serine protease 2 (MASP-2), with a key function of thrombin activation and fibrin mesh formation." (PMID 36901751, 2023). "In this regard, it has been shown that deposition of the mannose binding lectin (MBL)-associated serine protease MASP2 occurs in the microvasculature of the lung and skin of COVID-19 patients, suggesting systemic activation of the Lectin pathway (LP)." (PMID 35250994, 2022). "In COVID-19, the complement system has a procoagulant effect through the action of mannose-associated serine protease-2 (MASP-2), which is a component of the lectin pathway, and its role is to activate thrombin and to form a fibrin mesh." (PMID 36295093, 2022). "MBL Associated Serine Protease 2 (MASP2) that promotes complement cascade activation; variants in MASP2 resulting in its reduced expression are noted in asymptomatic elderly COVID-19 patients." (PMID 36143338, 2022). "Among them the mannose binding lectin serine protease 2 (MASP-2) has also been implicated in the altered lectin complement pathway resulting in accelerated inflammatory responses and lung damages involved in COVID-19 pathogenesis." (PMID 33435561, 2021). "Narsoplimab, a high-affinity fully human immunoglobulin gamma 4 (IgG4), has been reported to block the lectin pathway by binding to mannan-binding lectin-associated serine protease-2 (MASP-2), which binds to COVID-19 N protein in disease progression." (PMID 34199430, 2021). "MASP-1 and/or MASP-2 present an increased expression in patients with COVID-19 risk factors: diabetes, arterial hypertension and cardiovascular disease, chronic kidney disease, chronic obstructive pulmonary disease, and cerebrovascular disease." (PMID 33729332, 2021). "Tissue damage consistent with complement-mediated microvascular injury has been observed in the lung and/or skin of patients with severe COVID-19, with significant deposition of the LP effector enzyme MASP-2, a hallmark of profound activation of the LP." (PMID 34290717, 2021). "More recently, MASP-2 has been implicated as one of the factors contributing to aggravated lung injury in COVID-19 pathogenesis." (PMID 33133089, 2020). "Since increased levels of TCC have been associated with disease severity in COVID-19 patients, MASP-2 might be considered a possible point of therapeutic intervention as well as a possible prognostic marker." (PMID 35816998, 2023). "A striking deposition of C5b-9, C4d, and the mannose binding lectin (MBL)-associated serine protease (MASP2) was found in the microvasculature of pulmonary and cutaneous pathologic specimens from COVID-19 patients, suggesting sustained, systemic activation of the complement cascade." (PMID 35250994, 2022). "Similar to COVID-19 patient lung tissues, the in vivo association between MASP-2 and the SARS-CoV N protein was demonstrated by in situ PLA in the lungs of the Ad-SARS N pre-infected, LPS-challenged mice, and a higher level of the cleaved MASP-2 fragment was also observed in these mice." (PMID 36100602, 2022). "In our study we could confirm positive correlation of complement activation with severity of COVID-19 on organ level since lung injury scores as well as tubular injury scores were associated with increased activation of MASP-2." (PMID 35237273, 2022). "Furthermore, studies investigating MASP1 and MASP2 polymorphisms that may modulate the levels of MASPs in COVID-19 patients, can contribute to a greater understanding of the disease." (PMID 33729332, 2021).
COVID-19 (continued). "Moreover, the presence of terminal complement components including C5b-9 (membrane attack complex/MAC), C4d, and mannose-binding lectin (MBL)-associated serine protease (MASP2) within the pulmonary microvasculature and purpuric skin lesions of deceased COVID-19 patients." (PMID 34786557, 2020). "The ameliorating effect of MASP-2 inhibition on the severity of COVID-19 pathology is reflected by a significant reduction in the proinflammatory activation of brain microglia in HG4-treated mice." (PMID 37878754, 2024). "Deposited MASP-2, a key protease of the lectin pathway, was detected in the lungs and kidneys of patients who died from COVID-19." (PMID 39000451, 2024). "MASP-2 levels in hospitalized individuals with COVID-19 correlated with the inflammation marker C-reactive protein." (PMID 35816998, 2023). "The lectin pathway was suggested to mediate complement activation in SARS-CoV-2 infection, and the MASP2-inhibitor narsoplimab had a promising effect in critically ill COVID-19 patients." (PMID 37771589, 2023). "MASP-2 correlated with complement activation and inflammatory markers in COVID-19 patients, underscoring a possible role of MASP-2 in COVID-19 pathophysiology." (PMID 35816998, 2023). "We also observed this when testing MASP-2 in a group of pre-COVID-19 plasma samples obtained from Danish blood donors." (PMID 35816998, 2023). "MASP-2 deposition in the kidneys of COVID-19 patients was seen in peritubular capillaries (PTC) and especially in tubular basement membranes (TBM), with almost 10 times higher levels than in the control group." (PMID 35237273, 2022). "In particular, hyaline membranes in the lungs of patients with COVID-19 showed strong MASP-2 deposition." (PMID 35237273, 2022). "investigating local complement activation in small sample numbers of lungs and skin from patients with COVID-19, showing MASP-2 and C4d deposition in intraalveolar septa." (PMID 35237273, 2022). "Compartment-specific analysis showed that MASP-2 was detectable in the bronchioli, the larger vessels, and within alveolar infiltrates in controls and COVID-19 cases in comparable quantities." (PMID 35237273, 2022). "Our findings provide a rationale for the clinical use of anti-MASP-2 antibodies and anti-C5a antibodies for COVID-19 treatment." (PMID 36100602, 2022). "In parallel to the localization of the other complement factors C3d and MASP-2, we detected C5b-9 in the alveolar septa significantly more frequently in the COVID-19 group." (PMID 35237273, 2022). "Nevertheless, increased deposition in the peritubular capillaries (PTC) and tubular basement membranes (TBM) was recorded in the samples of COVID-19 patients, similar to MASP-2 and C3d." (PMID 35237273, 2022). "Complement activation was significantly stronger in lung samples from patients with COVID-19 via the lectin and alternative pathway as indicated by deposition of MASP-2, CFD, C3d and C5b9." (PMID 35237273, 2022). "In contrast, MASP-2 as an activator of the lectin pathway was significantly more abundant in the lungs of patients with COVID-19 compared to controls." (PMID 35237273, 2022). "Evidence proved that MASP-2, the lectin pathway’s serine protease, bound with coronavirus N protein and was abnormally highly expressed in lung tissue of COVID-19 patients." (PMID 33811541, 2021). "Increased levels of the PRM H-ficolin and associated proteases and proteins MASP-2 and MAp19 associated with severe disease in Asian patients, and the association of reduced MASP-3 with severe COVID-19 was detected in White patients only." (PMID 33995410, 2021). "The finding of MASP2 localized in the pulmonary inter-alveolar septa of one COVID-19 patient led Magro and coworkers to conclude that C is activated through the lectin pathway." (PMID 34440207, 2021). "Our data are consistent with recent reports describing deposits of MBL and MASP2 in affected tissues of COVID-19 patients and in vitro MBL pathway activation by recombinant SARS-CoV2 proteins." (PMID 34567008, 2021).
COVID-19 (continued). "In line, pulmonary vascular MASP-2 deposits were demonstrated in an autopsy study of critically ill COVID-19 patients, and MBL concentrations were higher in patients with thromboembolic events." (PMID 34777382, 2021). "Microvascular deposits of C5b-9, C4d, and MASP-2 in patients with COVID-19 suggest the role of the lectin pathway in proinflammatory sequelae." (PMID 34924021, 2021). "The lectin pathway inhibitor, narsoplimab, which exerts its activity by blocking MASP-2, has been shown to prevent EC damage and thrombotic microangiopathy; recovery and survival was observed in all COVID-19 patients treated with narsoplimab." (PMID 34868042, 2021). "C inhibitors, especially those targeting C3 or MASP-2, are exciting options for treating COVID-19 and consequent PE." (PMID 34868042, 2021). "We demonstrated associations between COVID-19 and circulating levels of lectin PRMs, (M- and H-ficolin, CL-L1 and CL-K1) and proteases (MASP-2, MAp19 and MASP-3)." (PMID 33995410, 2021). "Recombinant anti-MASP2 (Narsoplimab), which inhibits lectin pathway activation, has been tested as a COVID-19 therapeutic, resulting in rapid reduction in inflammatory and cell death markers (CRP, IL-6, IL-8, LHD) in six treated patients with ARDS." (PMID 34930107, 2021). "demonstrated, that the SARS-CoV-2 nucleocapsid protein bound to MASP-2 and activated complement; blockade of this interaction improved the survival of mice with COVID-19 nucleocapsid potentiated LPS-induced pneumonia." (PMID 33584662, 2020). "In the material clogging plasma adsorbers used for extracorporeal therapy of patients with COVID-19 C3 was the dominant protein but collectin 11 and MASP-2 were also identified." (PMID 33584662, 2020). "Further, the N protein of SARS-CoV2 was found to activate MASP-2, leading to the aberrant complement activation and deposition of MASP-2 and C4 in the lung tissue of severely affected COVID-19 patients." (PMID 33133089, 2020). "In another study, extensive deposition of C5b-9, C4d, and MASP-2 was observed in the postmortem lungs of COVID-19 patients." (PMID 33133089, 2020). "The systemic activation of complement mediated by MBL in SARS-CoV-2 has also been demonstrated by the co-localization of MASP2 with the spike protein (S) in the lungs of COVID-19 patients." (PMID 33133089, 2020). "Compared to COVID-19 glomerular MASP-2 expression was higher in DIC, comparable in Ctrl, slightly lower in ATI and did not occur at all in HUS." (PMID 33584662, 2020). "Treatment of COVID-19 patients with Narsoplimab, an inhibitory anti-MASP-2 antibody, had beneficial effect and strongly suggested that endothelial injury-induced activation of MASP-2 and the LP play a central role in the pathophysiology of COVID-19-related lung injury." (PMID 39000451, 2024). "However, in patients admitted to the hospital with COVID-19, a significant elevation of MASP-2 concentration was observed compared with controls." (PMID 35816998, 2023). "Recently, several lines of evidence indicate that MASP-2 might be involved in the pathophysiology of COVID-19." (PMID 35816998, 2023). "Mannose-binding lectin-associated serine protease 2 (MASP-2) is the main activator of the lectin complement pathway and has been suggested to be involved in the pathophysiology of coronavirus disease 2019 (COVID-19)." (PMID 35816998, 2023). "However, the pathophysiology of COVID-19 is complex, and we also observed a slight overall inverse correlation of MASP-2 levels with increasing age and male sex in infected individuals, both associated with fatal outcome in COVID-19 patients." (PMID 35816998, 2023). "Thus, to further address the possible role of MASP-2 in COVID-19 and other diseases, we generated and characterized a panel of mouse monoclonal antibodies (mAbs) against human MASP-2 and established a reliable and sensitive MASP-2 sandwich ELISA." (PMID 35816998, 2023).
COVID-19 (continued). "Alternatively, this subgroup of most severe cases might exhibit consumption of MASP-2 through activation, as this has also been shown for C3 in COVID-19." (PMID 35816998, 2023). "However, in kidneys only MASP-2 correlated with C3d and C5b-9, indicating that COVID-19 mediated complement activation is here restricted to the lectin pathway." (PMID 35237273, 2022). "The crucial roles of MASP-2-involved complement activation in viral pathogenesis may direct the development of therapies for COVID-19." (PMID 36100602, 2022). "As to inflammatory mediators in COVID-19 affected skin, terminal complement C5b-9 and MASP2 (lectin complement pathway) deposition are prominent in skin biopsies of severely ill COVID-19 patients with livedoid or purpuric cutaneous reactions that clinically suggest vasculitis." (PMID 36684608, 2022). "Furthermore, MPO-positive neutrophils were found in significantly higher numbers in lungs and kidneys of COVID-19 patients and correlated with local MASP-2 deposition." (PMID 35237273, 2022). "The increased deposition of MBL, MASP-2, C3b, C4b, and C5b-9 on endothelial cells in COVID-19 patients is similar to the pathophysiology demonstrated in aHUS, which may serve to explain COVID-19’s potential triggering function of aHUS." (PMID 34944087, 2021). "The lung microvasculature of severe COVID-19 cases also present deposits of MASP-2, C5b-9 and C4d." (PMID 33729332, 2021). "The overactivation of coagulation in the initial phase of COVID-19, generating high levels of D-dimers, thrombocytopenia, and moderate prothrombin time prolongation, seems to be caused by the combined action of MASP-1/MASP-2 and thrombin." (PMID 33729332, 2021). "In brief, despite nonconclusive studies, the available data suggested favorable outcomes in a small number of patients with severe COVID-19 treated either with C1 inhibitor, MASP-2 monoclonal antibodies, compstatin-based complement C3 inhibitor, anti-C5 drugs, or C5a-C5aR1 antagonists." (PMID 34567008, 2021). "Interestingly, Narsoplimab, a fully humanized immunoglobulin gamma 4 (IgG4) monoclonal antibody against MASP-2 that inhibits LP functional activity, has been used successfully in treatment of critically ill, mechanical ventilation-dependent COVID-19 patients." (PMID 34290717, 2021). "However, anti-MASP-2 monoclonal antibody act as a new potential treatment strategy in COVID-19 is needed to confirm in the future." (PMID 33811541, 2021). "In light of our present results, and the encouraging performance of our clinical candidate MASP-2 inhibitor Narsoplimab in recently published clinical trials, we suggest that the targeting of MASP-2 provides an unsurpassed window of therapeutic efficacy for the treatment of severe COVID-19." (PMID 34290717, 2021). "The increased levels of complement cascade components were found in COVID-19 patients, such as C5b-9, C4d and MASP2, indicating that NLRP3 inflammasome may be activated in COVID-19 patients in a complement cascade-dependent manner." (PMID 34150848, 2021). "Apart from COVID-19 specimens, MASP-2 was detected in glomeruli with DIC and ATI." (PMID 33584662, 2020). "Also, in lung tissue from patients with non-resolvable COVID-19 (long COVID), elevated mRNA expression of MASP-2 and associated complement factors (C4a/C4b) suggests sustained lectin and classical pathway activity contributing to progressive fibrosis." (PMID 40869200, 2025). "We observed a slight but significant decrease in MASP-2 concentration in those COVID-19 patients who died during the observation period, which seems to be counterintuitive to the notion that elevated complement activation might be associated with disease severity." (PMID 35816998, 2023). "Furthermore, extensive deposition of MASP-2 in the capillaries and venules of small bowel thrombotic microvascular injury in COVID-19 has also been reported, and endothelial complement staining patterns colocalized with staining of SARS-CoV-2 membrane and spike proteins." (PMID 34290717, 2021).